MTOR (mechanistic target of rapamycin kinase)
Diseases named in the same sentence as MTOR in open-access papers (continued):
Sharing a sentence is not in itself a finding about the gene and the disease.
esophageal cancer (90 papers, 2012 to 2025). A primary or metastatic malignant neoplasm involving the esophagus. "It should be noted that the MTOR rs2295080 polymorphism has been suggested to be associated with clinical outcomes in esophageal cancer patients treated with chemoradiotherapy." (PMID 23209702, 2012). "Several polymorphisms, such as rs2295080, rs11121704, and rs12139042, have been shown to be significantly associated with lung and esophageal cancer, but more attention should be given to the association of mTOR polymorphisms with treatment response to inhibitors of the mTOR pathway." (PMID 27462867, 2016). "Hyperactivation of the mTOR/AKT/PI3K pathway was observed alongside increased mTOR expression in esophageal carcinoma samples compared to normal tissue." (PMID 40754657, 2025). "SFN inhibits esophageal cancer cells proliferation, triggering senescence of esophageal cancer cells by promoting ROS accumulation to induce DNA damage, modulating the mTOR/TEF3 axis to interfere with autophagy, and promoting lysosomal abnormalities." (PMID 38902597, 2024). "To investigate the role of MTOR in esophageal cancer, we constructed MTOR knockdown cell lines, KYSE30 and mEC25, using siRNA technology." (PMID 39742278, 2024). "Key focus areas include its impact on insulin signaling, AMP-activated protein kinase (AMPK) activation, and the mTOR pathway, which collectively contribute to its role in mitigating esophageal cancer progression." (PMID 38474224, 2024). "Functional assays revealed that MTOR knockdown significantly reduced colony formation efficiency and cell proliferation in esophageal cancer cells." (PMID 39742278, 2024). "Ginsenoside Rh4 inhibits aerobic glycolysis and inhibits PD-L1 expression through the AKT/mTOR pathway in esophageal cancer." (PMID 36768213, 2023). "PP121 also exerts cytotoxic effects in human esophageal cancer cells via Akt/mammalian target of rapamycin (mTOR) and nuclear factor kappa-B (NFκB) signaling." (PMID 37936054, 2023). "TRIM44 was also found to facilitate the EMT process by activating the Akt/mTOR pathway and thus promoting the metastasis of human esophageal cancer cells." (PMID 36249749, 2022). "TRIM44 significantly enhances the proliferation, migration, and invasion of human esophageal cancer cells by participating in the AKT/mTOR signaling pathway and phosphorylation of its downstream target STAT3." (PMID 36249749, 2022). "At the same time, some literature has confirmed that Phosphatidylinositol 3-kinase/AKT/Mammalian Target of Rapamycin (PI3K/AKT/mTOR) can be used as an immunotherapy target for esophageal cancer by affecting the expression of microRNA." (PMID 35434132, 2022). "Investigation of inhibitors targeting mTOR demonstrated that the development of drugs related to the PI3K/Akt/mTOR pathway is promising for treating esophageal cancer." (PMID 35989326, 2022). "HRAS mutations were known to be oncogenic; it was demonstrated in vitro that mutant HRAS hyperactivated MAPK and mTOR pathways in various cancer cell lines including lung, bladder, and oesophageal cancer." (PMID 35621690, 2022). "Based on these observations, we concluded that CPT-induced ROS production modulated the AMPK/mTOR/ULK1 pathway to induce autophagy in esophageal cancer cells." (PMID 33898327, 2021). "Recent investigations have documented that PI3K/AKT/mTOR cascade mediates apoptosis of non-small lung cancer, esophageal cancer, as well as myeloid leukemia cancer." (PMID 34821587, 2021). "SNPs can also have prognostic implications, as carriers of some mTOR polymorphisms have a lower survival not only in RCC but also in other malignancies, such as esophageal cancer." (PMID 34070677, 2021). "In our study, we elucidate a novel mechanism of the NF-κB/AMPK/mTOR/ULK1 pathway in CPT-induced protective autophagy in esophageal cancer cells, which provides a sound rationale for combinational anti-ESCC therapy with CPT and inhibition AMPK/ULK1 pathway." (PMID 33898327, 2021).
esophageal cancer (continued). "Recently, the mTOR signaling pathway has also been reported to induce the apoptosis of non-small lung cancer, esophageal cancer and myeloid leukemia cancer." (PMID 32513155, 2020). "Taken together, these results suggest that Rk3 can trigger apoptosis and autophagy in esophageal cancer through regulation of the PI3K/Akt/mTOR signaling pathway." (PMID 31091245, 2019). "The crosstalk between TNF-α and the Hh pathway has been reinforced by the finding that blockage of the mTOR pathway enhances the suppressive effect of the Hh inhibitor in esophageal carcinoma." (PMID 29695137, 2018). "In esophageal cancer, metformin inhibits esophageal cancer cell growth and sensitizes cells to the cytotoxic effects of 5-fluorouracil (5-FU) by targeting CSCs and mTOR." (PMID 28126011, 2017). "Here, we show that mutant HRAS hyperactivates the RAS and the mTOR pathway in various cancer cell lines including lung, bladder and esophageal cancer." (PMID 26544513, 2015). "In esophageal cancer, mTOR/S6 kinase signaling was shown to phosphorylate GLI1, promoting its transcriptional activity and tumor growth." (PMID 25749378, 2015). "In the present study, mTOR signaling was increased by ionizing radiation in the esophageal carcinoma Eca109 cells." (PMID 25009644, 2014). "Modulating the PI3K/Akt/mTOR signaling pathway might alter the effect of gefitinib in treating esophagus cancer." (PMID 40227333, 2025). "Additionally, MTOR has been identified as a potential therapeutic target in esophageal cancer, underscoring its critical role in tumor progression." (PMID 39742278, 2024). "Through knockdown of the MTOR gene in esophageal cancer cells, we found that reducing MTOR expression significantly inhibits tumor cell proliferation and colony formation, suppresses tumor growth rate in a mouse subcutaneous tumor model, and prolongs survival in mice." (PMID 39742278, 2024). "Notably, knockdown of MTOR in esophageal cancer cell lines significantly inhibited cell proliferation and colony formation, while in vivo experiments demonstrated reduced tumor growth rates and prolonged survival in mouse models." (PMID 39742278, 2024). "Additionally, mTOR and HDAC inhibitors converge on the TXNIP/thioredoxin pathway and cause oxidative stress and apoptosis in esophageal cancer." (PMID 36661507, 2022). "Our research comprehensively investigates the anti-tumor effect of CUDC-907 in vitro and in vivo, suggesting the efficacious inhibition of CUDC-907 on the proliferation, migration, and invasion of esophageal cancer cells and the induction autophagy via mTOR inhibition and LCN2 downregulation." (PMID 35989326, 2022). "Moreover, echinatin, another flavonoid, induced apoptosis and autophagy by inhibiting Akt and mTOR in esophageal cancer." (PMID 35884773, 2022). "This study reveals that mTOR can suppress CSCs via autophagy in esophageal cancer." (PMID 35406578, 2022). "TRIM44 promoted human esophageal cancer progression via the AKT/mTOR pathway." (PMID 31823782, 2019). "Moreover, we discovered that Rk3 contemporaneously induced apoptosis and autophagy by suppressing the PI3K/Akt/mTOR pathway in esophageal cancer cells." (PMID 31091245, 2019). "To determine whether the expression of V-ATPase V1E1 was associated with PKM2, we measured the concomitant expression of V-ATPase V1E1, p-PKM2, PKM2, and mTOR in esophageal cancer tissues." (PMID 27384996, 2016). "Likewise, cotreatment with the SMO inhibitor GDC-0449 and the mTOR inhibitor RAD001 suppressed tumor growth of esophageal cancer in vivo." (PMID 25749378, 2015). "This indicated that the inhibition of mTOR by Rap may effectively block the pro-survival response of esophageal carcinoma cells to radiation, and that mTOR inhibition may present a method for enhancing the efficacy of radiotherapy." (PMID 25009644, 2014).
esophageal cancer (continued). "The aim of the present study was to investigate whether radiation induces the mammalian target of rapamycin (Rap) (mTOR) signaling pathway in esophageal carcinoma Eca109 cells, and whether mTOR inhibition by rapamycin increases Eca109 cell radiosensitivity." (PMID 25009644, 2014). "We hypothesize that mTOR inhibition with Rap may exhibit a greater increase in the radiosensitivity of esophageal carcinoma in vivo." (PMID 25009644, 2014). "Thus, mTOR can inhibit cancer stemness through autophagy in esophageal cancer." (PMID 35406578, 2022). "Therefore, targeting mTOR protein with ethyl ferulate may provide antineoplastic effects against esophageal cancer." (PMID 35155187, 2021). "In conclusion, the present study is the first to clarify that Rk3 can inhibit Eca109 and KYSE150 cell proliferation through activating apoptosis and autophagy by blocking the PI3K/Akt/mTOR pathway, suggesting that Rk3 may be a promising antitumor agent for esophageal cancer." (PMID 31091245, 2019). "Therefore, whether mTOR inhibition enhances the radiosensitivity of esophageal carcinoma in vivo also requires further study." (PMID 25009644, 2014). "However, whether mTOR inhibition enhances radiation-induced DNA damage in esophageal carcinoma cells remains unclear." (PMID 25009644, 2014). "MYH9 also serves as a marker and prognostic indicator for esophageal cancer stem cells, promoting tumorigenesis via the PI3K/AKT/mTOR axis." (PMID 39988672, 2025). "In our investigation of ESCC's sensitivity to mTOR inhibitors, we initially assessed the half-maximal inhibitory concentration (IC50) of rapamycin across different esophageal cancer cell lines." (PMID 38725843, 2024). "In summary, shikonin instigates EC9706 cell apoptosis and autophagy using the target AMPK/mTOR/ULK signal pathway axis, which provides a potential new target to treat human esophageal cancer." (PMID 39502521, 2024). "Further, recently study founded that Neuritin suppresses oesophageal cancer growth and up‐regulates Kv4.2‐mediated transient outward K+ current through the PI3K/Akt/mTOR pathway in rat cerebellar granule neurons." (PMID 39187917, 2024). "Previous studies showed that knocking down apelin significantly suppressed cell proliferation and migration and promoted cell apoptosis in esophageal cancer cells in vitro, potentially by activating PI3K/mTOR signaling pathway." (PMID 37968758, 2023). "In oesophageal cancer cells, GPR176 silencing was shown to ameliorate proliferation and induce apoptosis by either inactivating PI3K/Akt/mTOR or decreasing Bcl-2/Bax." (PMID 37584712, 2023). "In esophageal carcinoma cell lines, high MCM7 expression induced cell proliferation, colony formation and migration by regulating the AKT1/mTOR messenger system." (PMID 34144903, 2022). "In human esophageal cancer, TRIM44 was involved in the AKT/mTOR signaling pathway and STAT3 phosphorylation." (PMID 33391405, 2021). "Based on “BRCAness” principle, our recent study found that methylation of NRN1 was a novel synthetic lethal marker for PI3K-Akt-mTOR and ATR inhibitors in human esophageal cancer." (PMID 34539742, 2021). "For example, active crosstalk between TNF-α/mTOR/S6K1 and the Hh pathway has been observed in esophageal carcinoma." (PMID 29695137, 2018). "In fact, mutations that activate the PI3K (phosphatidylinositol-3-kinase)-mTOR pathway are frequently found in many cancers, including AIDS-related lymphomas, and esophageal cancer." (PMID 28640831, 2017).
esophageal cancer (continued). "To further confirm that inhibition of AKT/mTOR and MEK/ERK contribute to esophageal cancer cell migration, we applied the ERK inhibitor U0126 and the AKT inhibitor LY294002 to Eca109 cells and measure their effect using wound healing assay." (PMID 25973684, 2015). "First, knockdown experiments in esophageal cancer cell lines revealed that NEFH is connected with the AKT pathway via Gsk3ß27, and, moreover, it has been reported that AKT/mTOR pathway alterations occur in RCC and affect prognosis of patients." (PMID 24464810, 2014). "Ethyl ferulate is an mTOR inhibitor that can suppress ESCC progression and may be a novel candidate compound for esophageal cancer chemoprevention." (PMID 35155187, 2021). "Silencing of MCM7 inhibited the phosphorylation of AKT1 and mTOR in both esophageal cancer cell lines, suggesting that MCM7 might promote cancer development and poor survival outcomes via activating the AKT1/mTOR signaling pathway." (PMID 32089988, 2020). "Interestingly, miR-218 could inhibit cell proliferation, promote cell apoptosis, induce cell cycle arrested in G0/G1 phase, as well as increase DDP sensitivity of esophageal cancer cells through suppressing phosphorylation of PI3K, AKT, and mTOR." (PMID 34881242, 2021). "An mTOR inhibitor could not chemosensitize apoptosis incompetent esophageal cancer cells, whereas lithium could." (PMID 26248051, 2015).
Hyperinsulinemia (86 papers, 2012 to 2026). An increased concentration of insulin in the blood. "Specifically, the cardiac tissue of 8-week-old MO offspring mice showed cardiac hypertrophy associated with hyperinsulinemia and activation of insulin signaling pathways through increased phosphorylated Akt-1 (Ser473) and mTOR (Thr 2448)." (PMID 37512552, 2023). "Hyperinsulinemia was associated with a down-regulation of insulin related-genes only in adipose tissue, whereas expression of liver mammalian target of rapamicyn (mTOR) was increased." (PMID 23226562, 2012). "While PI3K/AKT/mTOR signalling plays a critical role in cancer, targeting this pathway with single node inhibitors has limited efficacy due to several known factors such as pathway feedback reactivation, co-occurring pathway mutations, and systemic glucose dysregulation leading to hyperinsulinemia." (PMID 40360883, 2025). "Among them, the PI3K/Akt/mTOR axis links hyperinsulinemia and nutrient excess to oncogenic signalling, thereby promoting uncontrolled proliferation and resistance to apoptosis." (PMID 41071622, 2026). "Recent evidence further elucidates how hyperinsulinemia directly stimulates endometrial cell proliferation via PI3K/Akt/mTOR pathways, creating a shared oncogenic microenvironment across these conditions." (PMID 40718420, 2025). "PCOS patients often have IR, where hyperinsulinemia inhibits miR-338-3p transcription via PI3K/Akt/mTOR pathway activation." (PMID 40652291, 2025). "High insulin levels in hyperinsulinemia activate insulin/IGF signaling pathways followed by the activation of (PI3K)/Akt/mammalian rapamycin (mTOR) and MAPK signaling pathways, thus promoting cancer cell growth, survival, and mobility." (PMID 36834693, 2023). "First, previous fundamental research found that IR was linked to hyperinsulinemia, which activates the PI3K/Akt/mTOR/S6K signaling pathway in cancer." (PMID 36138391, 2022). "Its downregulation leads to hyperinsulinemia and, through drosophila insulin-like protein 2 (Dilp2), activates mTOR and induces tumorigenesis of oncogenic scribble (scrib) cells by allowing them to avoid epithelial cell competition." (PMID 33562380, 2021). "Constitutive activation of the mammalian target of rapamycin (mTOR) pathway has been postulated as a mechanism for hyperinsulinism and β-cell hyperplasia in diffuse CHI." (PMID 32482020, 2021). "Our data oppose the view that mTOR inhibitors provide new opportunities for the treatment of patients with hyperinsulinism." (PMID 28410602, 2017). "Augmented MPS and enhanced mTOR and p70S6K1 signalling in response to hyperaminoacidemia-hyperinsulinemia in elderly volunteers." (PMID 26610527, 2015). "Hyperinsulinemia is known to increase mTOR/p70 S6K pathway and increased IRS-1/2 serine phosphorylation indicating insulin resistance state of a tissue." (PMID 24460834, 2014). "We show that MS symptoms appear before those of SLE and propose a possible interconnection of both diseases through hyperinsulinemia and mammalian target of rapamicyn (mTOR) up-regulation." (PMID 23226562, 2012). "This suggests that dietary management may prevent excessive placental overgrowth by limiting hyperinsulinemia and subsequent mTOR upregulation." (PMID 40136665, 2025). "In addition, AMPK, a kinase with antiproliferative and HPH mitigating effects that inhibits mTOR, is inhibited by overweight and hyperinsulinemia, with overactivation of mTOR being observed under these conditions." (PMID 39456805, 2024). "The mTOR signaling might be involved in the effect of maternal hyperinsulinemia on the endometrium receptivity process." (PMID 38104082, 2023). "A trend toward hyperinsulinemia at 10 weeks of HFD was observed in mTOR-KOPlacenta mice (P = 0.09)." (PMID 34032632, 2021). "Metformin, by inhibiting mTOR, suppresses induced by hyperinsulinemia scrib cells proliferation." (PMID 33562380, 2021). "The over-activation of the Akt/mTOR pathway by hyperinsulinemia plays a key role in this shift." (PMID 28651594, 2017).